DEFB131A (defensin beta 131A)
Description:
Has antibacterial activity (Probable). Upon stimulation with lipoteichoic acid, promotes cytokines and chemokines production and secretion.
Synonyms: DEFB-31; DEFB131
Tractability: Antibody: UniProt places it where antibodies can reach, with high confidence; UniProt predicts a signal peptide or a membrane-spanning region; its Gene Ontology location is reachable by antibodies, with medium confidence.
Gene: Protein-coding gene on chromosome 4 (9,444,414 to 9,450,666, forward strand). Ensembl gene ENSG00000186146.
Subcellular location: Secreted
Pathways (Reactome):
Immune System: Beta defensins; Defensins
Gene Ontology:
Molecular function: protein binding
Biological process: innate immune response
Cellular component: extracellular region
Genetic constraint (gnomAD): Loss-of-function variants: 3 observed, 2.36 expected, observed/expected ratio (o/e) 1.27, 90% interval 0.51 to 1.91. That is too few expected variants to judge how well the gene tolerates losing a copy. Missense variants: 83 observed, 52.49 expected, observed/expected ratio (o/e) 1.58, 90% interval 1.32 to 1.87. Synonymous variants: 22 observed, 16.36 expected, observed/expected ratio (o/e) 1.34, 90% interval 0.96 to 1.84.
Homologues: Orthologues: chimpanzee DEFB131A (99% identical), dog CBD131 (54% identical), rat Defb43 (54% identical), mouse Defb43 (53% identical). Paralogues in human: DEFB131B (94% identical), DEFB129 (27% identical), DEFB135 (27% identical), DEFB123 (24% identical), DEFB128 (24% identical), DEFB132 (24% identical), DEFB134 (24% identical), DEFB108B (23% identical), DEFB115 (23% identical), DEFB118 (23% identical), DEFB124 (23% identical), DEFB127 (23% identical), and 7 more.
Diseases named in the same sentence as DEFB131A in open-access papers:
DEFB131A is named in the same sentence as 1 disease in open-access papers, as found by Europe PMC text mining. Sharing a sentence is not in itself a finding about the gene and the disease.
DEFB131A shares sentences with these, for which no sentence is quoted: bacterial infection (1 paper).